TAS2R18P (taste 2 receptor member 18, pseudogene)
Synonyms: T2R18; TAS2R65; PS4; T2R65; TAS2R18; TAS2R65P
Gene: Unprocessed pseudogene on chromosome 12 (11,158,785 to 11,159,694, reverse strand). Ensembl gene ENSG00000256981.
Diseases named in the same sentence as TAS2R18P in open-access papers:
TAS2R18P is named in the same sentence as 8 diseases in open-access papers, as found by Europe PMC text mining. Sharing a sentence is not in itself a finding about the gene and the disease.
TAS2R18P shares sentences with these, for which no sentence is quoted: Anophthalmia (1 paper); autosomal recessive deafness- (1); breast adenocarcinoma (1); cancer (1); Diabetes (1); microphthalmia (1); paracoccidioidomycosis (1); tumor (1).